LEP (leptin)
Diseases named in the same sentence as LEP in open-access papers (continued):
Sharing a sentence is not in itself a finding about the gene and the disease.
Insulin resistance (continued). "The association of leptin with hyperglycemia and its significant correlation with serum glucose and insulin levels in PCOS thus explain its role in metabolic impairments, which may occur due to insulin resistance." (PMID 25587271, 2014). "Furthermore, our data suggest that among the overweight/obese population those with insulin resistance had a significant higher level of leptin concentration compared to those overweight/obese who were not insulin resistant even after controlling for a number of potential confounding factors." (PMID 23349940, 2013). "The absence of an association between insulin resistance and leptin independent of BMI or waist circumference in this high risk group suggests this molecule may not be a key driver to hyperinsulinemia in the advanced stages of dysmetabolism." (PMID 23671875, 2013). "Thus, in the present study, improvement of insulin resistance by the AI extract might be associated with decreased gene expression and/or production of cytokines such as TNFα, IL-6, MCP1, and leptin." (PMID 23401719, 2013). "Therefore, it was reasonable to propose that leptin resistance may act synergistically with insulin resistance to result in type 2 diabetes development." (PMID 23590862, 2013). "In GDM, leptin has a more debatable role, since it appears to be elevated in women with GDM but, after adjustment for BMI and insulin resistance, it is shown to be decreased or even unaltered, while it has also been associated with insulin resistance in pregnancy." (PMID 22550485, 2012). "Taken together, accumulating evidence strongly suggests that a single molecule, suppressor of cytokine signaling 3 (SOCS3), may mediate both leptin and insulin resistance due to its ability to inhibit leptin and insulin signaling in both central and peripheral target tissues." (PMID 23115649, 2012). "However, some adipocytokines, including serum leptin, are associated with MetS and insulin resistance in non-obese as well as obese subjects." (PMID 22537054, 2012). "Therefore, we can speculate that the increased levels of leptin may derive from this increased adipose tissue and may be involved in the early development of insulin resistance." (PMID 20298581, 2010). "In these conditions, the drastic plasma reduction of leptin and adiponectin associated with CLA treatment, induces fatty liver and hyperinsulinaemia, not through the direct induction of hepatic lipid synthesis and insulin resistance, but because of the scarcity of the adipose tissue." (PMID 20180981, 2010). "Thus, obesity is strongly associated with OSA, insulin resistance, leptin, and CRP levels and may be the major confounding factor in the relationship of OSA to insulin resistance and cardiovascular morbidity." (PMID 20224753, 2010). "CLA-induced insulin resistance may be related to the alterations of plasma leptin levels." (PMID 19761624, 2009). "High VAT content promotes inflammation and tumor progression via cytokine secretion (leptin, resistin, IL-6, and TNF- α), angiogenesis, and insulin resistance." (PMID 40699302, 2026). "For example, leptin concentrations have shown positive correlations with REE in children and adolescents, and indices of insulin resistance such as HOMA have exhibited weak but significant relationships with REE in pediatric cohorts." (PMID 41594297, 2026). "Insulin resistance was estimated using HOMA-IR, and the leptin-to-adiponectin ratio (LAR)-a marker of fasting and postprandial insulin sensitivity-was calculated." (PMID 41618682, 2026). "The plasma leptin levels in FRUCT animals seem to be directly correlated with elevated plasma insulin concentration and insulin resistance observed in this group of animals." (PMID 40227203, 2025). "The leptin-to-adiponectin ratio, or LAR, is a composite biomarker that represents the balance between leptin (pro-inflammatory, insulin-resistance-promoting) and adiponectin (anti-inflammatory, insulin-sensitizing)." (PMID 40722840, 2025).
Insulin resistance (continued). "Although leptin and adiponectin help regulate energy and metabolism, other variables such as TNF-α, IL-6, and resistin can worsen insulin resistance." (PMID 40002424, 2025). "VAT is metabolically active and by secreting free fatty acids and adipokines such as leptin, TNF-α, and IL-6 contributes to fostering systemic inflammation, endothelial dysfunction, and insulin resistance." (PMID 41141356, 2025). "In humans, healthy individuals with higher circulating leptin levels are often accompanied by lower insulin sensitivity independent of adiposity, suggesting that hyperleptinemia could be a compensatory response to insulin resistance, which might lead to more adverse effects on metabolic outcomes." (PMID 40066865, 2025). "The current study has revealed a number of indicators of potential insulin resistance in TREK-1 knockout mice, including an observed decrease in ACC, and adiponectin, rise in OGTT and leptin levels, and enlargement of adipocyte size in TREK-1 knockout mice." (PMID 40057491, 2025). "Acupuncture has been demonstrated to reduce insulin and leptin levels in T2DM patients, increase serum adiponectin levels, alleviate insulin resistance, and regulate glucose and lipid metabolism." (PMID 40568559, 2025). "As leptin resistance and insulin resistance occur simultaneously in T2DM, it is also certainly possible that a synergism of diminished leptin and insulin response leads to reduced CVP neuronal function." (PMID 40078371, 2025). "Hyperinsulinemia and insulin resistance increase mitogenic IGF-1 signaling, while dysregulated adipokines, particularly elevated leptin and reduced adiponectin, promote cellular proliferation and impair tumor suppression." (PMID 40722646, 2025). "First, VAT is highly proinflammatory, producing adipokines such as leptin, TNF-α, and IL-6, which promote endothelial dysfunction, inflammation, and insulin resistance." (PMID 41141356, 2025). "Recent reviews also indicate that anthocyanins regulate leptin signaling by increasing ObR receptor expression and activating the JAK2/STAT3 and PI3K/Akt pathways, which improves leptin sensitivity and reduces insulin resistance." (PMID 41374016, 2025). "ST reduced BW, epididymal and visceral fat depots, triglycerides, total cholesterol, glucose, leptin, and tumor necrosis factor (TNF)-α levels while improving insulin resistance." (PMID 40862455, 2025). "Vitamin E has preventive and protective effects on MASLD by improving hepatic steatosis (FLI, L/S ratio), insulin resistance (HOMA-IR), oxidative stress (MDA), inflammation (hs-CRP, TNF-α, IL-6, leptin, adiponectin), and hepatocyte apoptosis (CK18-M30)." (PMID 40668532, 2025). "In summary, we found that administering CJE to db/db mice at 200 mg/kg improved fasting blood glucose, serum insulin, serum leptin, and HOMA-IR levels, indicating a potential improvement in insulin resistance." (PMID 39815341, 2025). "A rat skeletal muscle cell line’s stimulation with recombinant leptin decreased the phosphorylation of insulin receptor substrate-1 (IRS-1) and impaired glucose uptake, indicating that leptin promotes insulin resistance." (PMID 39943080, 2025). "Insulin resistance can impair signaling pathways that regulate APLNR expression and leptin secretion." (PMID 41302116, 2025). "Cardiometabolic risk was assessed as a latent variable using the following indicators: homeostatic model assessment for insulin resistance (HOMA-IR), leptin, mean arterial pressure (MAP), and waist circumference (WC)." (PMID 41572970, 2025). "The probiotic also reduced serum insulin levels, the homeostasis model assessment of insulin resistance (HOMA-IR), and leptin levels, indicating improved metabolic regulation." (PMID 40218922, 2025). "Homeostasis Model Assessment of Insulin Resistance (HOMA-IR), and adiponectin/leptin ratio were also calculated." (PMID 39127712, 2024).
Insulin resistance (continued). "SCFAs help improve insulin secretion, reduce insulin resistance, suppress glucose production, and decrease food intake by regulating the secretion of hormones like GLP-1, leptin, and ghrelin, thereby playing a positive role in DM prevention and management." (PMID 39610877, 2024). "In particular, resistin, leptin, and PAI-1 induce insulin resistance by interfering with the expression of insulin receptor substrate-1 (IRS-1), negatively impacting insulin signaling in PLTs." (PMID 39858414, 2024). "ER stress promotes insulin resistance through complex mechanisms, including a decrease in adiponectin levels, which increases mTOR activity, IRS phosphorylation, and leptin resistance." (PMID 39063184, 2024). "Elevated leptin and PAI-1 levels exacerbate insulin resistance, interfere with IRS-1, and negatively impact insulin signaling in PLT membranes." (PMID 39858414, 2024). "The deteriorated insulin resistance in B3galt5△IEC mice was further evidenced by elevated serum levels of insulin and leptin." (PMID 39004626, 2024). "The present study evaluated the performance of plasma leptin, plasma adiponectin, and LAR as surrogates of insulin resistance in prepubertal children." (PMID 38289144, 2024). "ISF intake at 1 g/kg reduced body weight gain, serum total cholesterol, free cholesterol, NEFA, leptin and hepatic TAG and DHT-induced insulin resistance (P < 0·01)." (PMID 38826091, 2024). "Hypothyroidism can lead to insulin resistance, possibly due to changes in GLUT4 translocation, the effects of leptin, and an increase in free fatty acids." (PMID 39735651, 2024). "Insulin resistance in MASLD arises from an imbalance between insulin sensitizing adipokines, such as adiponectin and leptin, and cytokines that promote insulin resistance like TNF-α." (PMID 39064282, 2024). "Effects on fasting glucose and insulin, Homeostatic Model Assessment of Insulin Resistance (HOMA-IR), HbA1c, adiponectin, leptin, IL-6, TNF-α, and C-reactive protein (CRP) in exercise vs control groups were analyzed using random effects meta-analysis." (PMID 38253590, 2024). "Several insulin resistance surrogates based on fasting plasma samples have been extensively used in epidemiological studies, such as the homeostasis model assessment of insulin resistance (HOMA-IR) index and the plasma leptin/adiponectin ratio (LAR)." (PMID 38289144, 2024). "The representative adipokines secreted from adipose tissues with an increased plasma leptin, resistin, and TNF-α, and a reduced plasma adiponectin are related to systemic insulin resistance." (PMID 39065815, 2024). "In insulin-resistant mice fed a high-fat diet (HFD) or in leptin knockout mice, elevation of TMAO through diet significantly exacerbated insulin resistance in these mice." (PMID 38514666, 2024). "Circulating biomarkers including insulin resistance (HOMA index), adipokines (resistin, adiponectin, leptin), choline pathway metabolites (TMAO, betaine, choline), and endothelial progenitor cells (EPCs) were measured." (PMID 39339817, 2024). "The pathogenesis of metabolic syndrome is mainly mediated by increased free fatty acids leading to insulin resistance and chronic low-grade inflammation induced by pro-inflammatory cytokines such as IL-6, TMF-α, and leptin." (PMID 39139641, 2024). "In humans, PLAG1 methylation is related to leptin concentrations in cord blood and PLAG1 expression is correlated with increased body fat mass, insulin resistance, and fatty acid concentrations." (PMID 38671859, 2024). "The AT insulin resistance (ATIR) index and ATIR/adiponectin and adiponectin/leptin ratios were calculated." (PMID 37391843, 2023). "The VLCHF diet was effective for favorable changes in the homeostasis model assessment of insulin resistance (HOMA-IR), Adiponectin/Leptin ratio and diastolic blood pressure." (PMID 38141101, 2023).
Insulin resistance (continued). "The present data demonstrated a positive correlation of metabolic factors, including FBS, HbA1c, insulin resistance, waist circumference, and BMI with serum hs-CRP, leptin levels, and the semen parameters." (PMID 37208686, 2023). "Leptin’s proinflammatory effects also increase cytokines such as TNF-alpha, IL-1, IL-2, IL-2 and MCP-1, leading to accelerated atherosclerosis, insulin resistance and endothelial dysfunction." (PMID 37371050, 2023). "Other beneficial effects observed were improved insulin resistance, glucose transporter- 4 (GLUT- 4) mRNA expression, blood glucose and leptin levels." (PMID 37103396, 2023). "During pregnancy, insulin resistance increases, partly due to elevated levels of circulating adipocytokines: TNF-α, resistin, and leptin." (PMID 38069155, 2023). "Conversely, through altering the leptin-AMPK pathway, UA contributes to aberrant metabolic processes in adipose tissue, leading to increased blood NEFA and insulin resistance." (PMID 36864452, 2023). "More importantly, accumulating evidences demonstrated that the obese animals and humans who displayed leptin resistance may directly contribute to the suppression of lipid oxidation in insulin-sensitive organs and ultimately lead to accumulation of lipids and insulin resistance." (PMID 37114144, 2023). "Gluconeogenesis disorder is the most typical feature of insulin resistance in which HNF-4α synergizes with PGC-1α, FOXO1 and other key enzymes to induce gluconeogenesis, and Leptin regulates the AMPK pathway by inhibiting HNF-4α and promoting SIRT1 expression." (PMID 37705071, 2023). "Inflammation, renin-angiotensin system-sympathetic nervous system activation and insulin resistance, endothelial dysfunction Shared genes among hypertension, NAFLD, fibrosis, and inflammation include LEP, ADIPOQ, AHR and TGFB1." (PMID 37664266, 2023). "Excessive intake of free fatty acids by hepatocytes can lead to insulin resistance and systemic hyperinsulinemia; third, excess VAT can lead to leptin resistance and increased leptin secretion; and fourth, VAT is a marker of ectopic fat deposition." (PMID 35432188, 2022). "We noticed that the BSME decreased the expression levels of insulin resistance and macrophage chemoattractant proteins, such as TNF-α, IL-6, leptin and STAT-6, in maturing-adipocyte-secreted proteins." (PMID 35209178, 2022). "Thus, it is evident that serum leptin levels may be a useful marker of insulin resistance." (PMID 35355566, 2022). "Body composition, plasma leptin, adiponectin, chemerin, omentin-1, lipids, C-reactive protein (CRP), and the homeostasis model assessment index for insulin resistance (HOMA-IR) were assessed before and after the HIIT program." (PMID 35741374, 2022). "The goal of the study was to examine if there was a link between the leptin (LEP) (rs77990) as well as LEPR gene (rs1137101) with insulin resistance and lipid profile, in order to determine the extent to which the leptin gene polymorphism could cause insulin resistance in pregnant women." (PMID 36128550, 2022). "Some adipocytokines such as adiponectin, leptin and resistin play important roles in the development of NAFLD by acting on liver by producing increased inflammation reaction and increasing insulin resistance." (PMID 36072931, 2022). "Baseline evaluation of homeostasis model assessment-insulin resistance (HOMA-IR), plasma glucose, insulin, leptin and adiponectin levels, and systolic and diastolic blood pressure (SBP and DBP) of patients was done." (PMID 35350513, 2022). "Adipose tissue can be used as an endocrine organ to secrete adipokines to regulate glucose balance in the body, and leptin (LEP) can regulate glucose and lipid metabolism, which can be regarded as a marker of insulin resistance." (PMID 35456474, 2022).
Insulin resistance (continued). "Moreover, an induction of cell death in the hypothalamus and/or the whole brain can mimic metabolic inflammation that may mediate the development of central leptin and insulin resistance, resulting in a broad range of metabolic disorders including overeating, glucose intolerance and hypertension." (PMID 36439719, 2022). "Third, as well as being an energy-storing organ, adipose tissue is the largest endocrine organ producing adiponectin, leptin, TNF-α, and IL-6, which leads to systemic inflammation and insulin resistance, thereby further exacerbating NAFLD." (PMID 35453642, 2022). "Serum leptin levels of the patients were correlated with the FSI, fasting plasma glucose (FPG), homeostasis model assessment of insulin resistance (HOMA-IR), body mass index (BMI), and total testosterone levels." (PMID 35355566, 2022). "Interestingly, in cats, increased plasma leptin concentrations are associated with insulin resistance, regardless of whether cats were lean or obese." (PMID 35968003, 2022). "In the colonic content, Coprococcus was significantly negatively correlated with insulin resistance and positively correlated with the TBA level, and oscillospira was highly significantly negatively correlated with serum leptin levels (p < 0.05)." (PMID 35807856, 2022). "Firstly, the improvement of glucose metabolism (with a reduction of circulating glucose, insulin, and leptin levels) is favorable in obese subjects with CKD, often characterized by insulin resistance." (PMID 35811945, 2022). "Although leptin, TNF-α, resistin, and adiponectin are all representative adipokines, the first three are positively correlated with insulin resistance and adiponectin is negatively correlated." (PMID 37073221, 2022). "The ratio correlates with insulin resistance more closely than a surrogate of insulin resistance such as the HOMA index, adiponectin, or leptin alone." (PMID 36422274, 2022). "An uncomplicated pregnancy is characterized by insulin resistance, which increases with advancing gestation in order to secure a high glucose supply to the fetus; this may be attributed to hormones and cytokines, including TNFa, IL-6 and adipokines (resistin and leptin) produced by the placenta." (PMID 35885550, 2022). "It reduces the action of adipocytokines such as leptin, TNF-α, and IL-6, as well as oxidative stress, which leads to an improvement of insulin resistance." (PMID 35742443, 2022). "Up-regulates insulin and leptin levels to down-regulate body weight, fat, GLU, Insulin resistance, GOT, GPT." (PMID 35548468, 2022). "As expected, circulating parameters related to insulin resistance (e.g., fasting circulating glucose and HOMA index), as well as circulating leptin levels, were increased as a result of HF diet feeding (U Mann–Whitney, p < 0.05)." (PMID 35684076, 2022). "Paradoxically, although these individuals exhibit high levels of leptin expression in WAT, the elevated levels of circulating leptin fail to reduce adiposity, improve energy homeostasis, or reduce insulin resistance." (PMID 35527735, 2022). "The CAFR diet in females decreased BW, Lee index, and adiposity and improved metabolic risk factors (decreased serum glucose, insulin, triacylglycerides, and insulin resistance), while CAFR in males decreased only adiposity and leptin levels." (PMID 36615803, 2022). "Taken together, leptin affects the occurrence and development of PCOS by regulating the reproductive endocrine axis and ovarian steroid production, and by participating in insulin resistance." (PMID 36289764, 2022). "In conclusion, leptin affects the occurrence and development of PCOS by regulating the reproductive endocrine axis, ovarian steroidogenesis and by participating in insulin resistance." (PMID 36289764, 2022). "Compared with normal-weight peers, fat insulin resistance is positively correlated with systemic and visceral obesity, fasting blood sugar, insulin resistance index HOMA-IR, and leptin." (PMID 35242879, 2022).